RB1 (RB transcriptional corepressor 1)
Diseases named in the same sentence as RB1 in open-access papers (continued):
Sharing a sentence is not in itself a finding about the gene and the disease.
small cell carcinoma (23 papers, 2010 to 2025). A neuroendocrine carcinoma composed of small malignant cells which are often said to resemble "oat cells" under the microscope. "RB1 loss is frequently seen in both the adenocarcinoma and small-cell carcinoma components of mixed tumors." (PMID 37686633, 2023). "Loss of Rb1 protein expression was detected in all the 15 small-cell carcinomas and 12/82 of the high-grade squamous cell carcinomas (15%)." (PMID 32556556, 2021). "In the p16-positive high-grade squamous cell carcinoma group, only 4 cases presented the same expression pattern (p16 overexpression/Rb1 protein loss) as that of small-cell carcinomas." (PMID 32556556, 2021). "In squamous cell carcinoma, the occurrences of CDKN2A (27%) and PTEN (17%) mutations become more frequent compared to other cancer subtypes, while in small cell carcinoma, RB1 mutations become more prevalent (40%)." (PMID 28373672, 2017). "Loss of RB1 function is common in primary small cell cancer of the prostate or lung, and in animal models it promotes development of small cell carcinoma." (PMID 28228136, 2017). "Loss of RB1 by deletion is another common event in prostatic small cell carcinoma as Rb protein loss was found by immunohistochemistry in as many as 90% of small cell carcinoma cases (26 of 29) with RB1 allelic loss in 85% of cases (11 of 13)." (PMID 25699233, 2015). "The p16 overexpression via RB1 alteration was on the one hand demonstrated in highly aggressive tumors, such as small-cell carcinomas of the lung and esophagus." (PMID 32556556, 2021). "The pathways identified in this study agree with the pathways observed to be altered by siRNA-mediated silencing of the RB1 gene in human non-small cell carcinoma cells, H1299, in culture." (PMID 20664703, 2010). "Moreover, RB1 protein loss occurs nearly universally in small cell carcinomas, while only a minority of high-grade primary or metastatic acinar carcinomas with NED harbor RB1 alterations." (PMID 39796175, 2025). "The patients with small-cell carcinoma, all of whom expressed p16, had significantly worse survival than those with p16-positive high-grade squamous cell carcinoma despite their common p16/Rb1 signaling activation status." (PMID 32556556, 2021). "This suggests that the p16/Rb1 signaling might not be a single regulatory mechanism that is associated with the aggressive behavior of the small-cell carcinomas." (PMID 32556556, 2021).
small cell carcinoma (continued). "Interestingly, 5 out of 6 cases of high-grade squamous cell carcinomas with focal or a single-cell p16 expression also showed loss of Rb1 expression, which might suggest an incomplete activation of p16 protein despite the same p16/Rb1 signaling activation status as observed in small-cell carcinomas." (PMID 32556556, 2021).
Obesity (22 papers, 2010 to 2023). Accumulation of substantial excess body fat. "Because of the close association between hepatic steatosis and obesity, we assessed the effect of Rb1 on hepatic lipid deposition into assessment." (PMID 35639355, 2022). "In our future work, the regulatory effects of BBR+Rb1 on the upstream pathway of NF-κB signaling will be further investigated to better understand the mechanism underlying the potential anti-obesity effect of BBR+Rb1." (PMID 34699329, 2021). "For instance, adipose-specific RB1-deficient mice are resistant to high-fat diet (HFD)-induced obesity and display increased mitochondrial activity in white and brown adipose tissues." (PMID 29176962, 2017). "However, it is unknown whether Rb1 can improve obesity-associated inflammation and central leptin resistance." (PMID 24675731, 2014). "Rb1 can improve the relative abundance of key bacterial genera in the gastrointestinal tract and, thus, improve obesity, which is conducive to type 2 diabetes." (PMID 37049846, 2023). "Mice treated with Rb1 inhibited HFD-induced obesity and improved glucose intolerance and fat liver and adipose function." (PMID 35639355, 2022). "To further study the effect of Rb1 on obesity, we cultured C2C12 cells and 3T3-L1 cells in vitro with and without Rb1 treatment respectively." (PMID 35639355, 2022). "In this study, we investigated the impact of Rb1 oral supplementation on high fat diet (HFD) induced obesity mice, and explored its mechanism in regulating blood glucose." (PMID 34899310, 2021). "In the present study, we investigated the effects of BBR and Rb1 on TNF-α-induced inflammation in adipocytes to explore the potential synergetic effect of the two drugs on obesity and metabolic syndrome." (PMID 34699329, 2021). "To confirm the effects of Rb1 on body weight in obese mice, we established a mouse model of obesity through HFD feeding." (PMID 32821266, 2020). "The aim of the present study was to determine the protective effects of Rb1 on glycolipid metabolism under obesity conditions and its mechanisms and to reveal the signaling pathways involved." (PMID 32821266, 2020). "In conclusion, we suggest Rb1 as a potential lipolytic and thermogenic therapeutic agent which can be used for obesity treatment." (PMID 31680950, 2019). "Further, conditional deletion of Rb1 in POMC neurons resulted in cell cycle reentry, neuronal apoptosis, and obesity; however, in contrast, deleting Rb1 in the antagonizing AgRP/NPY neurons was well tolerated." (PMID 30185666, 2018). "For example, Rb1 has a great potential for exerting anti-obesity effects by stimulating c-Fos expression in brain areas involved in energy homeostasis; Rb1 also promotes glucose homeostasis by increasing insulin sensitivity." (PMID 29114222, 2017). "Rb1 is a representative component of ginseng possesses several properties, including anti-obesity, anti-oxidative stress, and anti-fatigue, anti-angiogenesis etc.." (PMID 29180961, 2017). "Last, we found that the retinoblastoma protein RB1, which also participates in the PPARA pathway, is associated with insulin resistance, obesity, and metabolic disturbances in mice." (PMID 28549478, 2017). "PPARγ might be the potential target for Rb1 in obesity-related insulin resistance, which would be a therapy for early T2D treatment." (PMID 37049846, 2023). "Previous studies have shown that Rb1 may partially ameliorate obesity through the MSTN/FNDC5 signaling pathway." (PMID 37049846, 2023). "Furthermore, our results showed that the molecular mechanism of Rb1 inhibiting macrophage activation was through the activation of PPARγ in the obesity microenvironment." (PMID 37049846, 2023). "(2020) found that Rb1 could markedly diminish the body weights of mice with HFD-induced obesity and the mechanism involved was that Rb1 enhanced AQP7 expression both in vivo and in vitro." (PMID 35639355, 2022). "Our study provides important experimental evidence for the treatment of obesity by Rb1." (PMID 35639355, 2022).
Obesity (continued). "In this research, we explored the role of Rb1 in obesity and metabolic disturbances in mice." (PMID 35639355, 2022). "This study provides an alternative mechanism for Rb1 to treat metabolic disorders induced by obesity and that may contribute to the development of new nutraceutical-based remedies accordingly." (PMID 35516426, 2022). "To summarize, we demonstrate that Rb1 is a negative regulator of obesity." (PMID 35639355, 2022). "Rb1 can be used as an effective drug in the treatment of human obesity." (PMID 35639355, 2022). "Our results showed that Rb1 can be used as an effective drug in the treatment of human obesity." (PMID 35639355, 2022). "Our results showed that Rb1 may ameliorate obesity in part through the MSTN/FNDC5 signalling pathway." (PMID 35639355, 2022). "Through correlation analysis, we explored the multiscale mechanisms that might account for the therapeutic effect of Rb1 against obesity." (PMID 35516426, 2022). "It is a potential therapeutic that Rb1 may be for the treatment of obesity and obesity-related metabolic disorders." (PMID 35639355, 2022). "Therefore, we believe that BBR and Rb1 can be combined in future clinical therapeutic strategies for obesity management to achieve improved anti-obesity effects of the two compounds." (PMID 34699329, 2021). "known as a probiotic to ameliorate obesity and immune response, was markedly increased by Rb1." (PMID 34899310, 2021). "Our study indicated a potential role for Rb1 in the prevention and treatment of obesity." (PMID 32821266, 2020). "Thus, these preclinical studies demonstrate that Rb1 can potentially become an effective treatment for obesity, insulin resistance, and T2DM." (PMID 26359241, 2015). "In conclusion, Rb1 could affect the secretion and release of inflammatory factors through the important target of PPARγ, regulate the activation of macrophages, and further inhibit the occurrence of insulin resistance in obesity." (PMID 37049846, 2023). "This study provides a novel mechanism of Rb1 for the treatment of metabolic disorders induced by obesity, which may provide a therapeutic avenue for the development of new nutraceutical-based remedies for treating metabolic diseases, such as hyperlipidemia, insulin resistance, and type 2 diabetes." (PMID 35516426, 2022). "However, the mechanisms by which Rb1 regulates obesity remain to be explored." (PMID 35639355, 2022). "Rb1 may ameliorate obesity in part through the MSTN/FNDC5 signalling pathway." (PMID 35639355, 2022). "The anti-obesity function of Rb1 might be related to energy balance." (PMID 32821266, 2020). "Therefore, the data suggest that BG and Rb1 might be potential therapeutic candidates for the prevention and treatment of obesity." (PMID 31726767, 2019). "Based on this, we endeavored to evaluate the metabolic effects of the Rb1 and explore its regulatory role on gut microbiome and amino acid metabolism in HFD induced obesity and diabetes in mice." (PMID 34899310, 2021). "In our study, male C57BL/6 mice with obesity induced by a high-fat diet (HFD) and mature 3 T3-L1 adipocytes were used to investigate the role of Rb1 in lipid accumulation and explore its possible molecular mechanism in vivo and in vitro, respectively." (PMID 32821266, 2020).
prostate tumors (22 papers, 2013 to 2025). "The well-characterized tumor suppressor gene RB1 (retinoblastoma susceptibility gene) on 13q14.2 displayed significantly lower expression in AA breast and prostate tumors, which correlates with the greater loss of DNA we observed in AAs relative to EAs." (PMID 32819446, 2020). "Loss of RB1 in prostate tumor cells resulted in decreased expression of chemokines associated with immune infiltration and function, increased expression of multiple checkpoint ligands, as well as soluble factors resulting in decreased T cell migration." (PMID 30400835, 2018). "Several hypotheses could explain how the loss of Rb1 increases the crosstalk between prostate tumour cells and gut microbiota." (PMID 38654015, 2024). "Thus, our results have potential implications for the treatment of RB1 loss–driven prostate tumor growth and metastasis, and perhaps other RB1-deficient malignancies, with ferroptosis induction." (PMID 36928314, 2023). "Induction of ferroptosis suppresses RB1-deficient prostate tumor growth and metastasis." (PMID 36928314, 2023). "All together, our findings reveal the regulation of ferroptosis by the RB/E2F/ACSL4 axis and highlight the therapeutic potential of ferroptosis induction in the treatment of RB1 loss–driven prostate tumor growth and metastasis and perhaps other RB1-deficient malignancies." (PMID 36928314, 2023). "However, the large chromosomal deletions found in prostate tumors delete both RB1 and ELF1, and this response would be lost." (PMID 30603056, 2018). "Interestingly, the ELF1 locus is roughly 8 Mb away from RB1 on chromosome 13 and is often co-deleted in prostate tumors." (PMID 30603056, 2018). "Our findings that ELF1 promotes senescence in prostate cells could explain why RB1 is lost due to deletion, rather than mutation in prostate tumors." (PMID 30603056, 2018). "We noted that the ELF1 gene is located 8 mb from RB1, which is known to be deleted in some late stage prostate tumors, and from this dataset we see that ELF1 is often co-deleted with RB1." (PMID 30603056, 2018).
prostate tumors (continued). "In contrast, deletion of RB1 by itself showed no impact in prostate tumor development." (PMID 29600194, 2018).
squamous cell carcinoma (22 papers, 2013 to 2024). A carcinoma arising from squamous epithelial cells. "Interestingly, the p16 overexpression induced by dysregulation of RB1 appeared to have an association with tumor aggressiveness in high-grade squamous cell carcinoma." (PMID 32556556, 2021). "We immunolocalized p16 and Rb1 in 82 surgically resected esophageal high-grade squamous cell carcinomas (46 poorly differentiated and 36 basaloid squamous cell carcinomas) and 15 esophageal small-cell carcinomas in order to clarify the clinical and biological significance of p16." (PMID 32556556, 2021). "The p16 overexpression was associated with loss of Rb1 protein but not with HPV infection in both esophageal small-cell and high-grade squamous cell carcinomas." (PMID 32556556, 2021).